MTOR (mechanistic target of rapamycin kinase)
Diseases named in the same sentence as MTOR in open-access papers (continued):
Sharing a sentence is not in itself a finding about the gene and the disease.
epilepsy (continued). "IL-17, mainly derived from Th17 cells, is also increased though mTOR activation in epilepsy, which leads excessive pro-inflammatory cytokine expression and maintain the chronic inflammation." (PMID 35898503, 2022). "In recent years, the mTOR pathway has been considered as a new target for the treatment of epilepsy." (PMID 35173580, 2022). "Recent findings have highlighted the dysfunction of the mTOR pathway in epilepsy, and regulating this pathway by multi-drug regimen seems to be a feasible option." (PMID 36286014, 2022). "Mutations in other mTOR pathway genes, such as TSC1, TSC2, AKT3, MTOR, and PIK3CA, are linked to some epilepsy-related multisystem disorders (e.g., tuberous sclerosis complex; Nguyen and Bordey, 2021)." (PMID 35706428, 2022). "More importantly, a study directly examined the link between ion channel and mTOR pathway under the context of epilepsy." (PMID 35359577, 2022). "Consistently, RAD001 impedes the expression levels of PI3K, p-AKT, AKT, mTOR, and p-mTOR in epilepsy rats." (PMID 35485300, 2022). "In epilepsy, ncRNAs can regulate inflammatory cells and mediators by interacting with mTOR signaling during the intricate neuroinflammatory processes." (PMID 35898503, 2022). "Rapamycin’s inhibitory effect on mTOR activity and subsequently mossy fiber sprouting has been demonstrated numerous times using various models of epilepsy." (PMID 34658792, 2021). "Because seizure onset within this model is highly predictable, it is an ideal model to study mTOR-dependent epileptogenesis and to identify early cellular changes that eventually result in epilepsy." (PMID 34877936, 2021). "Presently, the MTOR inhibitor rapamycin and its analogs are the sole pathway-related drugs used clinically to treat epilepsy, primarily in tuberous sclerosis (TSC) patients with rare TSC1/2 deletion mutations which enhance downstream MTOR signaling." (PMID 34899181, 2021). "Based on the numerous studies proving the efficacy of rapamycin in suppressing seizures in animal models of mTOR hyperactivity Everolimus has been approved as treatment for epilepsy in TSC in 2018." (PMID 34828352, 2021). "Taken together, our findings show that ubtor regulates motor hyperactivity and epilepsy-like behaviors by elevating neuronal activity and activating mTOR signaling." (PMID 34309811, 2021). "Our results further emphasize the role of aberrant regulation of mTOR signaling in NPRL3 mutation–related seizures and NPRL3 LOF in the genesis of epilepsy." (PMID 34868250, 2021). "In the brains of infants with TSC, a vicious cycle of epileptic encephalopathy is formed by mTOR hyperactivity, abnormal synaptic structure/function, and excessive epileptic discharges, further worsening epilepsy and intellectual/behavioral disorders." (PMID 34206526, 2021). "MTOR-related HI is a recognizableneurocutaneous phenotype of patterned dyspigmentation, epilepsy, intellectualdeficiency, and brain overgrowth, and a distinct subtype of hypomelanosisrelated to somatic mosaicism." (PMID 33833411, 2021). "Rapamycin, an inducer of mitophagy and inhibitor of mTOR, can prevent the further development of epilepsy in the early periods, whereas late treatment reduces seizure frequency in mice that already have epilepsy." (PMID 34937577, 2021). "In fact, around two-thirds of Vici syndrome patients present severe epilepsy with different types of seizures, suggesting the inclusion of the syndrome in the context of mTOR-related disorders." (PMID 34308255, 2021). "Since some forms of epilepsy are related to the upregulation of the mTOR pathway, different therapeutic strategies have been designed to inhibit this pathway." (PMID 34069559, 2021). "Taken together, our studies found that the ubtor gene plays a role in early spontaneous movement and epilepsy-like behaviors in zebrafish by regulating the mTOR signaling pathway and spinal interneuron activity." (PMID 34309811, 2021).
epilepsy (continued). "Using pharmacological and genetic approaches we showed that the mTOR-dependent epilepsy likely arises from altered axonal connectivity, through which distally connected (supposedly healthy) neurons are affected." (PMID 34038402, 2021). "The data from this paper plausibly link mTOR activation observed in epileptogenesis with the later appearance of mTOR activity in epilepsies." (PMID 34358226, 2021). "mTORopathies are defined as a co-occurring set of phenotypic symptoms, which are associated with disruptions of specific genes within the mTOR pathway, most often paralleled with ASD and epilepsy." (PMID 34828352, 2021). "This early precision medicine trial provided a precedent for further study of mTOR inhibitor therapy for epilepsy and neurodevelopmental disorders in the mTORopathies." (PMID 34632383, 2021). "From the phenotypes caused by single gene mutations (e.g., TSC, tuberous sclerosis), a role for the Mechanistic Target of Rapamycin (MTOR) pathway has been established in epilepsy." (PMID 34122302, 2021). "Alteration of mTOR activity results in neurological effects, like epilepsy, intellectual disability, and autism spectrum disorder (ASD)." (PMID 34298906, 2021). "Recent advances in the studies of TSC have provided clinicians with candidates for robust therapeutic measures to escape from the vicious cycle, such as vigabatrin, mTOR inhibitors, and epilepsy surgery." (PMID 34206526, 2021). "Focal cortical dysplasia type II results from somatic brain mutations in mechanistic target of rapamycin pathway activators MTOR, AKT3, PIK3CA and RHEB and is a major cause of drug-resistant epilepsy." (PMID 34632383, 2021). "The PI3K/Akt/mTOR pathway exhibits a significant role in neurodegenerative diseases such as epilepsy and Parkinson’s disease." (PMID 34832986, 2021). "In order to study the mechanism behind mTOR-dependent MCD-related epilepsy, we next assessed the reliability of seizure development using our RHEBp.P37L mutant model." (PMID 34038402, 2021). "Our study emphasizes inhibition of the TSC/mTOR signaling pathway as a promising therapeutic approach to target epilepsy in patients with TSC." (PMID 34877936, 2021). "Rapamycin and its analogs, that are currently in clinical use to treat epilepsy in TSC patients, curbed epileptiform activity in mouse models harboring TSC1/2, RHEB, MTOR, or PTEN mutations when administered long-term (>7-day)." (PMID 34899181, 2021). "Molecular target therapy with mTOR inhibitors has recently been proved to be efficacious for epilepsy in human TSC patients, and for autism in TSC model mice, indicating the possibility for pharmacological treatment of developmental synaptic disorders." (PMID 34206526, 2021). "It should be added that the elevated activity of mTOR signaling is a feature of not only ASDs but also other psychicand neurological diseases: Alzheimer’s disease (Pei, Hugon,2008), epilepsy, and even Down syndrome." (PMID 34901706, 2021). "The current state of research shows that modulation of mTOR activity allows us to successfully treat comorbidities of mTORopathies such as epilepsy." (PMID 34828352, 2021). "The recent studies supporting the modern approaches for the treatment of epilepsy have been deliberated with particular reference to the mTOR pathway, breakdown of the blood-brain barrier, and inflammatory pathways." (PMID 33923061, 2021). "The molecular mechanisms mediating the role of mTOR overactivation and epilepsy in the pathogenesis of ASD are only very partially understood." (PMID 33863288, 2021). "For example, circadian rhythms are known to be perturbed directly via the mTOR pathway, as well as influenced by epilepsy and anti-seizure medications." (PMID 34903167, 2021). "miR-155 induces autophagy through mTOR, and this effect is more obvious in the young mouse status epilepticus model, which strongly suggests the existence of this hypothetical pathway in epilepsy." (PMID 33776649, 2021).
epilepsy (continued). "Recent advancements in targeted therapy by mTOR inhibitors and epilepsy surgery can reduce the burden of illness and the effectiveness of these therapies should be a focus of further research." (PMID 31964424, 2020). "As an indication of an active role of mTOR in the pathogenesis of epilepsy, mTORC1 inhibitors such as the rapalogs decrease the frequency or severity of seizures in a disease with elevated mTORC1 activity." (PMID 32821949, 2020). "This emerged mainly from evidence indicating that rapamycin, a powerful mTOR inhibitor and autophagy inducer, strongly modulates a variety of seizure models and epilepsies." (PMID 32121250, 2020). "It is remarkable that, similar to autophagy failure, UPS alterations in epilepsy are bound to mTOR hyperactivation." (PMID 32121250, 2020). "The clear causative role of mTOR as epileptogenic driver, as well as implications of mTOR activation in acquired epilepsies, makes TSC an attractive disease model to utilize as translational prototype for epilepsy in general." (PMID 33041976, 2020). "Despite wide evidence suggesting a failure of autophagy in epileptogenesis and epilepsy-induced neuronal alterations, some controversies still exist which tone down viewpoints linking autophagy failure with most of the epilepsy-related mTOR alterations." (PMID 32121250, 2020). "In the present review, increasing evidence was presented indicating a link among both genetic and acquired forms of epilepsy with alterations in mTOR-dependent cell-clearing systems." (PMID 32121250, 2020). "On the other hand, administration of mTOR inhibitors in the early postnatal period resulted in preventing seizure onset or in making seizures cease if given after epilepsy onset." (PMID 32216820, 2020). "Based on the pharmacokinetics advantages and antiseizure efficacy, particularly of PQR620 inhibitor, it would be interesting to research the antiepileptic potential of mTOR inhibitors, both in chronic animal models of epilepsy and in drug-resistance epilepsy." (PMID 33202963, 2020). "TSC serves as a model for epilepsy, autism, and tumorigenesis and many other diseases involving the mTOR pathway." (PMID 32222129, 2020). "This review will focus on the role of glial dysfunction related to mTOR hyperactivity and its contribution to comorbidities, such as epilepsy and TANDs in TSC." (PMID 33041976, 2020). "A possible means by which alteration in BMAL1 activity leads to seizures and epilepsy is via the mTOR pathway." (PMID 32714261, 2020). "Several preclinical and some clinical studies have indicated that the hyperactivation of the mTOR signaling pathway appears involved in acquiring epilepsy." (PMID 33519354, 2020). "mTOR-related UPS dysfunctions beyond autophagy alterations are now emerging in the field of epilepsy as well." (PMID 32121250, 2020). "The hyperactivation of mTOR participates in epilepsy; the inhibition on this kinase results in beneficial anti-convulsive effects." (PMID 33250850, 2020). "It is known that one of the manifestations of epilepsy and autistic pathologies is increased activity of the mammalian target of rapamycin (mTOR) signaling pathway, which is the central link in the regulation of local cap-dependent translation at the synapse." (PMID 32921299, 2020). "mTOR hyperactivation signaling in epilepsy makes it an efficient target for therapeutic intervention and have driven the significant effort to pharmacologically target this pathway." (PMID 32973652, 2020). "They used a mouse model of tuberous sclerosis complex and showed that early treatment with rapamycin not only inhibits the activation of mTOR but also delays astrogliosis and hippocampal pyramidal cell disorganization, preventing the development of epilepsy." (PMID 33202963, 2020). "The expression of mTOR signaling-related proteins is abnormally increased in animal models of epilepsy." (PMID 32184723, 2020).
epilepsy (continued). "More recently, direct evidence has been provided indicating a solid correlation among mTOR-dependent autophagy, epileptogenesis and epilepsy-induced neuronal damage." (PMID 32121250, 2020). "Even though antiepileptic drugs, mTOR inhibitors, and surgical treatment can be chosen if necessary, the management of refractory epilepsy is still very intractable, attributing to the unclear etiopathogenesis." (PMID 33123575, 2020). "mTOR inhibitors have been shown to be effective in the treatment of other TSC manifestations including epilepsy, renal angiomyolipoma, and lymphangioleiomyomatosis." (PMID 31333563, 2019). "The dysregulation of mTOR is involved in human diseases including cancer, cardiovascular diseases, neurodegenerative diseases, and epilepsy." (PMID 31547370, 2019). "Other common treatments for treating FS were epilepsy surgery (in Belgium, Italy, and Spain) and mTOR inhibitors (in Sweden, Germany, and France)." (PMID 31708865, 2019). "In epilepsy models, mTOR inhibition has been shown to reduce neuronal death, nerve regeneration, and the development of spontaneous epilepsy." (PMID 31481868, 2019). "Other treatment options such as mammalian target of rapamycin (mTOR) inhibitors, the ketogenic diet (KD) and epilepsy surgery were used in <20% of the patients at baseline, and remained relatively stable over time." (PMID 31708865, 2019). "GAB Aergics were the most prescribed drugs for epilepsy, and mTOR inhibitors are dramatically replacing surgery in patients with SEGA, despite current recommendations proposing both treatment options." (PMID 31708865, 2019). "Still, further studies are needed to investigate the benefits of mTOR inhibition on TSC-related epilepsy in infancy and early childhood." (PMID 31053163, 2019). "Previous studies in various rodent epilepsy models have suggested that mammalian target of rapamycin (mTOR) inhibition with rapamycin has anti-epileptogenic potential." (PMID 30037344, 2018). "NS-Pten KO mice exhibit a number of phenotypes, including mTOR hyperactivation, neuronal cytomegaly, cortical and hippocampal disorganization, and epilepsy, which are evident after 4 to 6 weeks of postnatal development and worsen with age20–22,29." (PMID 29476105, 2018). "Mammalian target of rapamycin (mTOR) is actually retained a good candidate for epilepsy and epileptogenesis." (PMID 29566708, 2018). "Zeng and colleagues observed reduced mossy fiber sprouting in the rodent kainic acid model of epilepsy when the animals were treated with the mTOR antagonist rapamycin; a finding replicated by numerous other groups using multiple epilepsy models." (PMID 29774009, 2018). "For example, valproic acid, a HDACi utilized in the treatment of bipolar disorder and epilepsy, was shown to downregulate the mammalian target of rapamycin (mTOR), restoring OXPHOS, the driver of immune tolerance." (PMID 30564191, 2018). "Given the emerging involvement for mTOR signaling in voltage-gated ion channel expression, one candidate mechanism by which mTOR dysregulation promotes epilepsy in CD is through remodeling of voltage-gated ion channel expression." (PMID 29476105, 2018). "Aberrant activation of mTOR pathway is reported in various models of epilepsy, including FCD type II1." (PMID 30568293, 2018). "Disruption of the mTOR signaling pathway is a putative pathophysiologic mechanism of epileptogenesis in different models of lesional epilepsy in rodents and humans and has emerged as a possible therapeutic target for epilepsy." (PMID 28082152, 2018). "As opposed to classic epileptic encephalopathies in which seizures themselves cause cognitive impairment beyond the etiology, in TSC it is the molecular etiology—mTOR overactivation—that probably drives both the epilepsy and the encephalopathy/TAND." (PMID 28367137, 2017). "The mTOR signaling pathway has significant and distinct impacts on neurological diseases including epilepsy." (PMID 28966575, 2017).
epilepsy (continued). "The relative duration of epilepsy (normalized to age) also correlated positively to mTOR activation and negatively to myelination." (PMID 27750396, 2017). "Changes in the TSC1/2 gene responsible for tuberous sclerosis ultimately results in mTOR activity, leading to epilepsy." (PMID 28966575, 2017). "Findings that the epilepsy and behavioral deficits in mice can be rescued by mTOR inhibitors, offers a broad therapeutic window in which patients can potentially be treated." (PMID 29051493, 2017). "mTOR signaling pathway has been found to influence the immune response, tumorigenesis, brain development, and epilepsy." (PMID 28109197, 2017). "Several animal and human studies have shown that mTOR activation resulted in neuroexcitability, seizure, and epilepsy, which encouraged researchers to use mTOR inhibitors in seizure therapy." (PMID 28109197, 2017). "Noteworthy, administration of mTOR inhibitors is frequently beneficial for treating some neurological alterations such as epilepsy, autism, and learning disabilities." (PMID 29259984, 2017). "Control protein synthesis and autophagy through downstream PI3K-Akt-mTOR pathways that are known to be dysregulated in AD and epilepsy." (PMID 28966575, 2017). "Several animal and human studies have demonstrated that mTOR activation can result in neuroexcitability, seizure, and epilepsy." (PMID 28109197, 2017). "On the other hand, rapamycin, an mTOR inhibitor, has antiepileptogenic effects in kainic acid (KA)-induced and pilocarpine-induced models of epilepsy in animals." (PMID 26993296, 2017). "Continuous stimulation of synapses further activates mTOR/MAPK pathway reinforcing their effect on RBP-mediated expression control establishing the basis for epilepsy." (PMID 27855659, 2016). "Nevertheless, more insight is necessary to develop new diagnosis and therapy strategies for the treatment of epilepsy and to understand side effects of mTOR and MAPK inhibition." (PMID 27855659, 2016). "Various pre-clinical and clinical studies demonstrated that loss of function mutations of the genes encoding for the natural mTOR inhibitors TSC1 and TSC2 lead to aberrant mTOR signaling with consecutive development of cortical malformations and epilepsy." (PMID 27809914, 2016). "Clinical studies investigating the effect of mTOR inhibitors on TSC-related epilepsies are still limited and results are highly variable as both improvement and worsening of seizures have been reported." (PMID 27809914, 2016). "We propose that mTOR and MAPK regulate RBPs, thereby guiding the local expression of their target-mRNAs encoding for markers of epilepsy." (PMID 27855659, 2016). "A prominent cell signaling pathway activated in animal models of both TBI and epilepsy is the mammalian target of rapamycin (mTOR)." (PMID 26640431, 2015). "In epilepsy, that includes genes involved in chromatin remodeling and transcriptional regulation, synaptic vesicle trafficking, and mammalian target of rapamycin (mTOR) signaling." (PMID 26302787, 2015). "Inhibition of mTOR with rapamycin has shown promise as a potential modulator of epileptogenesis in several animal models of epilepsy, but cellular mechanisms linking mTOR expression and epileptogenesis are unclear." (PMID 26640431, 2015). "In attempting to develop more effective drugs for epilepsy, the mammalian target of rapamycin (mTOR) signaling pathway has recently been investigated as a regulator of epileptogenesis." (PMID 26248290, 2015). "Hyperactivation of mTOR signalling in neurological disease is best understood in the dominant genetic disorder tuberous sclerosis complex (TSC), which causes epilepsy and autism." (PMID 25210733, 2014). "Consistent with this idea, administration of the mTOR antagonist rapamycin has been found to inhibit mossy fiber sprouting and mitigate the development of spontaneous seizures in several models of epilepsy." (PMID 24672426, 2014).